LAPTM5 (lysosomal protein transmembrane 5)
Diseases named in the same sentence as LAPTM5 in open-access papers (continued):
Sharing a sentence is not in itself a finding about the gene and the disease.
Stroke (2 papers, 2022 to 2026). Sudden impairment of blood flow to a part of the brain due to occlusion or rupture of an artery to the brain. "In conclusion, LAPTM5 was demonstrated to be a novel modulator in the pathophysiology of brain I/R injury, and targeting LAPTM5 may be feasible as a stroke treatment." (PMID 36046710, 2022). "Thus, targeting LAPTM5 may be a promising therapeutic strategy for strokes." (PMID 36046710, 2022).
acute monocytic leukemia (1 paper, 2017). Acute monoblastic leukemia (AML-M5), is one of the most common subtypes of acute myeloid leukemia (AML) that is either comprised of more than 80% of monoblasts (AML-M5a) or 30-80% monoblasts with (pro)monocytic differentiation (AML-M5b). "LAPTM5 mRNA was detected in human peripheral T cells and immature malignant cells in the myeloid lineage such as chronic myelogenous leukemia K562 cells, promyelocytic leukemia HL-60 cells, promonocytic leukemia U937 cells, and acute monocytic leukemia THP-1 cells." (PMID 28464033, 2017).
AIDS (1 paper, 2021). A syndrome resulting from the acquired deficiency of cellular immunity caused by the human immunodeficiency virus (HIV). "Herein, we demonstrate the molecular mechanism used by Vpr to overcome LAPTM5 restriction in macrophages, providing a potential strategy for anti-HIV/AIDS therapeutics." (PMID 34140527, 2021).
amyloid (1 paper, 2023). "These genes, Thy1, Gfap, Tyrobp, Ctsd, Cst7, C1qb, Lyz2, Ctss, Trem2, Mpeg1, Hexb, Cd68, C1qb, C1qa, Ctsz, Grn, Laptm5, B2m, C1qc, Hexa, and Serpina3n, were increased in the 7-month-old 5XFAD model in the cortex and associated with amyloid plaque image patterns." (PMID 38036733, 2023).
asthma (1 paper, 2021). "KEGG pathway analysis results and GSVA results show that genes related to allograft rejection, asthma, and autoimmune thyroid disease pathways were enriched or upregulated in the LAPTM5, C1QC, SLCO2B1 and CSF1R high expression groups." (PMID 33428598, 2021).
diabetic nephropathy (1 paper, 2023). "Our study explored the same platform GEO dataset for diabetic nephropathy bioinformatics analysis and identified eight potential key genes (TYROBP, ITGB2, CD53, IL10RA, LAPTM5, CD48, C1QA, and IRF8), screened eight transcription factors, and identified 93 miRNA nodes." (PMID 37113991, 2023).
heart failure (1 paper, 2021). Inability of the heart to pump blood at an adequate rate to meet tissue metabolic requirements. "It is of far-reaching significance to explore molecular therapies targeting LAPTM5 for the treatment of heart failure." (PMID 34692792, 2021).
ischemic stroke (1 paper, 2022). A stroke disorder caused by obstruction of blood flow to the brain, due to thrombotic (local blood clot formation) or embolic (due to a blood clot or other material traveling from another site) event. "Furthermore, the mechanism by which LAPTM5 regulates brain I/R may depend on the ASK1-JNK/p38 signaling pathway, making LAPTM5 a highly promising method for ischemic stroke treatment." (PMID 36046710, 2022).
liver fibrosis (1 paper, 2021). "Furthermore, we demonstrated that single cell sequencing helps identifying novel, cell-specific markers such as COL15A1, ALOX5AP, and LAPTM5 that could further improve our understanding of liver fibrosis." (PMID 33922101, 2021).
liver steatosis (1 paper, 2023). "Overexpression of LAPTM5 attenuated liver steatosis, inflammatory response, and fibrosis." (PMID 37156795, 2023).
metastatic melanoma (1 paper, 2019). A melanoma that has spread from its primary site to another anatomic site. "LAPTM5 (lysosomal-associated protein transmembrane 5) is one of the top genes significantly associated with longer survival in metastatic melanoma, and ITGB2 (integrin beta 2) co-expression with HLA-DR participates in signal transduction, cell adhesion, and motility in neoplastic melanocytes." (PMID 31212865, 2019).
Myocardial fibrosis (1 paper, 2021). "Therefore, we examined the effect of LAPTM5 gene deletion on myocardial fibrosis." (PMID 34692792, 2021).
nasal polyps (1 paper, 2022). "Among these genes, PLEK was reported to be involved in CRSwNP but not correlated with M2 macrophages while AIF1, CD53 and LAPTM5 were related to M2 macrophages but not explored in nasal polyps." (PMID 36466903, 2022).
ovarian carcinoma (1 paper, 2021). A malignant neoplasm originating from the surface ovarian epithelium. "LAPTM5 (lysosomal‐associated protein transmembrane 5) is a membrane protein that can inhibit the expression of T‐cell receptor (TCR) and play a positive role in migration and invasion of ovarian cancer cell but play a negative regulator of T‐cell or B‐cell receptor downstream signalling." (PMID 33259129, 2021).
renal cell carcinoma (1 paper, 2023). "It was reported that LAPTM5 recruited WWP2 to mediate lysosomal degradation to drive lung metastases of renal cell carcinoma." (PMID 38102722, 2023).
urinary system tumor (1 paper, 2022). "ccRCC is a urinary system tumor, and the potential function of LAPTM5 in ccRCC remains to be fully explored and elucidated." (PMID 36385959, 2022).
viral infection (1 paper, 2021). "In summary, these data collectively demonstrate that LAPTM5 may carry HIV-1 Env to the lysosomes for degradation in primary MDMs to restrict viral infection." (PMID 34140527, 2021).
tumor (26 papers, 2009 to 2026). "As a lysosome-related transmembrane receptor, lysosomal-associated protein transmembrane 5 (LAPTM5) is involved in the occurrence and progression of some neoplastic diseases." (PMID 36602538, 2023). "Taken together, these results suggested the expression of LAPTM5 to be epigenetically down-regulated through DNA methylation in all NB cell lines and primary NB tumor samples and these conditions to be associated with the differentiation of tumors." (PMID 19787053, 2009). "Several studies have linked LAPTM5 to tumor development, with some suggesting that LAPTM5 functions as a tumor suppressor, while others argue that it may act as an oncoprotein." (PMID 39281638, 2024). "This suggests that LAPTM5 may be a candidate gene associated with familial WM, potentially linked to tumor clones." (PMID 39281638, 2024). "In our study, we found that LAPTM5 promoted proliferation, migration, and invasion of ccRCC cells in vitro and promoted tumor growth and survival in vivo; however, the underlying mechanisms remain unknown." (PMID 36385959, 2022). "Moreover, the results of TCGA database showed that LAPTM5 is significantly associated with tumor stage." (PMID 36385959, 2022). "Thus, it has been suggested that the loss of LAPTM5 can be associated with tumor progression by suppressing cell death; however, the biochemical mechanism underlying LAPTM5-mediated cell death remains unknown." (PMID 28464033, 2017). "In vivo experiments further confirmed that the depletion of LAPTM5 inhibited tumor growth and synergistically suppressed AML progression with AraC." (PMID 41912486, 2026). "The Future research should focus on: 1) Elucidating LAPTM5 mechanisms: Further studies are needed to dissect the molecular mechanisms by which LAPTM5 influences immune cell function and tumor progression." (PMID 39281638, 2024). "Downregulation of LAPTM5 disrupts this cell death pathway in the tumor parenchyma, subsequently promoting tumor development." (PMID 39281638, 2024). "Additional evidence demonstrates that LAPTM5 is differentially expressed in various tumor tissues, indicating its potential as a valuable marker for the diagnosis, treatment, and prognostic evaluation of tumors." (PMID 39281638, 2024). "On the other hand, in another study, LAPTM5 was found to act as a tumor suppressor and its inhibition actually promoted invasiveness of GBMs based on in vitro and in vivo experiments." (PMID 36945359, 2023). "LAPTM5 plays a negative regulatory role in T and B cell activation and is widely involved in tumor growth." (PMID 36385959, 2022). "Conversely, treatment of RencaLuM2b cells with DMH1, a small molecule inhibitor of the BMP receptors, reversed the inhibitory effect of Laptm5 knockdown on tumor sphere formation, suggesting the function of LAPTM5 was BMP-dependent." (PMID 35842443, 2022). "The wound healing and EdU assays demonstrate that the promoting effects of LAPTM5 on tumor proliferation were significantly weakened following RAC1 inhibitor treatment." (PMID 36385959, 2022). "As expected, LAPTM5 overexpression significantly enhanced the subcutaneous tumor initiation ability of Renca cells in mice." (PMID 35842443, 2022). "Conversely, silencing of Laptm5 markedly inhibited the subcutaneous tumor initiation ability of RencaLuM2b cells." (PMID 35842443, 2022). "The 786-0 cell line with LAPTM5 overexpression was injected into mice, and the time until tumor visualization was observed." (PMID 36385959, 2022). "The expression of LAPTM5, CSF1R, SLCO2B1 and C1QC was negatively associated with the tumor purity in the LUSC samples." (PMID 33428598, 2021). "In contrast, tumor recurrence was observed in one out of five shLAPTM5 tumors after initial shrinkage due to temozolomide treatment, supporting that LAPTM5 sensitized the CD40-positive U87MG tumor cells to temozolomide." (PMID 32582531, 2020). "Previous studies in other tumor entities already suggested the potential role of LAPTM5 in tumorigenesis." (PMID 32582531, 2020).
tumor (continued). "A further pathway analysis demonstrated that LAPTM5 mediates these tumor-suppressing and temozolomide-sensitizing effects by the inhibition of CD40-induced NFκB pathway activation." (PMID 32582531, 2020). "Our data suggest that LAPTM5 in GBMs show an opposite regulation to what has been observed in other tumor types." (PMID 31701625, 2020). "These LAPTM5-induced tumor-suppressing effects are mediated by the inhibition of the CD40-dependent NFκB pathway activation." (PMID 32582531, 2020). "Although LAPTM5 was also highly expressed in adjacent adrenal medulla cells within the tumor sections and weakly expressed in differentiated ganglion cells within GNs, its immunoreactivity in NB cells was much lower, regardless of the prognosis." (PMID 19787053, 2009). "The involvement of LAPTM5 in these processes suggests that its dysregulation might drive non-tumor deficits, emphasizing the need for further research into its functions in non-cancerous conditions." (PMID 39281638, 2024). "LAPTM5, a negative regulator of B cell maturation, was up‐regulated in tumour‐invaded TDLN than PT." (PMID 37491740, 2023). "Overall, these results indicate that LAPTM5 promotes tumor growth in vivo." (PMID 36385959, 2022). "Moreover, LAPTM5 overexpression promoted tumor proliferation, migration, and invasion in 786-0 and Caki-1cell lines, whereas LAPTM5 knockdown exerted the opposite effects." (PMID 36385959, 2022). "Moreover, the effects of LAPTM5 on tumor migration and invasion were eliminated following RAC1 inhibitor treatment." (PMID 36385959, 2022). "In addition, the tumor mass in the LAPTM5 overexpression group was significantly larger than that in the control group." (PMID 36385959, 2022). "Similarly, the tumor initiation ability of Renca cells in mouse renal subcapsular was also promoted by LAPTM5 overexpression when limited cells were implanted." (PMID 35842443, 2022). "However, in our study, we found that LAPTM5 was upregulated in ccRCC tumor tissues compared with that in the adjacent healthy tissues using Western blot and RT-PCR, which is consistent with previous bioinformatics analyses of kidney renal clear cell carcinoma." (PMID 36385959, 2022). "Moreover, treatment of Renca cells with 30 ng/mL BMP4 for 7 days markedly inhibited tumor sphere formation which was reversed by overexpression of LAPTM5." (PMID 35842443, 2022). "The mRNA expression of C1QC, CSF1R, LAPTM5 and SLCO2B1 was negatively associated with tumor purity." (PMID 33428598, 2021). "CD40 activated the NFκB pathway in cells depleted for LAPTM5 expression, promoting tumor growth and resistance to temozolomide, which could be overcome by NFκB inhibition." (PMID 32582531, 2020). "To validate our hypothesis that LAPTM5 acts as a potential tumor suppressor in CD40 high-expressing tumors, we evaluated its prognostic value in the TCGA-GBM cohort." (PMID 32582531, 2020). "Furthermore, we examined the level of LAPTM5 protein in NB tumor sections by conducting an immunohistochemical analysis using a specific antibody and confirmed that the protein is highly expressed in hematopoietic cells as reported." (PMID 19787053, 2009). "Furthermore, only one clinically detected tumor with LAPTM5-positive degenerating areas was classified as favorable (stage-2, well-differentiating)." (PMID 19787053, 2009). "In the context of tumors, elevated LAPTM5 levels in immune cells are associated with decreased cell membrane levels of T cell receptors (TCR) or B cell receptors (BCR), leading to impaired antigen presentation and immune escape, thereby promoting tumor progression." (PMID 39281638, 2024). "Next, we examined whether LAPTM5 could enhance tumor initiation in vivo." (PMID 35842443, 2022). "Moreover, our results demonstrate that LAPTM5 activates the Jun N-terminal kinase (JNK)/p38 axis by binding to Ras-related C3 botulinum toxin substrate 1 (RAC1), and the effects of LAPTM5 on tumor growth were attenuated following treatment with an RAC1 inhibitor." (PMID 36385959, 2022).
tumor (continued). "LAPTM5, a protein, is preferentially expressed in immune cells, and could interact with the Nedd4 family of ubiquitin ligases, which played an essential role in multiple tumor initiation and progression." (PMID 34888308, 2021). "In addition, we could not detect aberrant DNA methylation around the transcriptional start site of LAPTM5 in the ESCC tumor samples showing low expression, as is detected in NBs (data not shown)." (PMID 27058622, 2016). "Thus, it has been suggested that LAPTM5 expression and accumulation may contribute to PCD during NB tumor regression, and that LAPTM5 may function as a tumor suppressor in NB cells." (PMID 27058622, 2016). "Thus LAPTM5-mediated PCD is closely associated with the spontaneous regression of NBs and opens new avenues for exploring innovative clinical interventions for this tumor." (PMID 19787053, 2009). "High LAPTM5 expression is linked to the upregulation of immunosuppressive TOX pathway genes, CD8+ T cell exhaustion, and shorter overall survival of LUSC patients, suggesting that LAPTM5 may modulate tumor infiltration, antitumor immunity, and survival outcomes in LUSC patients." (PMID 39281638, 2024). "We selected four hub genes, LAPTM5, C1QC, CSF1R, and SLCO2B1, and analyzed their correlation with the tumor infiltration of 22 immune cell subsets using CIBERSORT and the prognosis of different immunity-related LUSC patient subtypes." (PMID 33428598, 2021). "Firstly, the expression levels of ITGAX, LAPTM5, and SERPINE1 in CCRCC tumor tissues are significantly higher than those in normal tissues adjacent to cancer according to GEPIA database." (PMID 33976979, 2021). "Further results showed that the ITGAX, LAPTM5, and SERPINE1 levels in CCRCC tumor tissues were significantly higher than those in normal tissues and were associated with poor prognosis." (PMID 33976979, 2021). "The promoter methylation levels of ITGAX, LAPTM5 and SERPINE1 in CCRCC tumor tissues were significantly lower than those in normal tissues." (PMID 33976979, 2021). "Due to the anti-tumor role of TNF-α and IL-12, the expression of LAPTM5 in macrophages could be a potential mechanism to improve ICB efficacy." (PMID 37492578, 2023). "Top underexpressed tumor suppressor candidates such as UBXN1, HNRNPA1, PPP1R15A, and LAPTM5 may also be contributing to tumor tissue formation through inhibition of apoptosis at initial stages of cancerogenesis." (PMID 36359790, 2022). "Western blotting and reverse transcription quantitative (RT-q) polymerase chain reaction (PCR) revealed that LAPTM5 expression was higher in the human ccRCC tumor group than that in the corresponding nontumor group." (PMID 36385959, 2022). "Our results demonstrated that LAPTM5 expression in patients with ccRCC was significantly higher in the tumor group than that in the adjacent nontumor group." (PMID 36385959, 2022). "The decrease of promoter methylation of ITGAX, LAPTM5 and SERPINE1 in CCRCC tumor tissues indicates that the high expression of key genes in CCRCC might be relevant to the low methylation level." (PMID 33976979, 2021). "Likewise, LAPTM5, which is the site of an insertion in tumor 7107, was identified in all three data sets, while NMYC, an insertion site in tumor 7105, was identified in two microarray data sets." (PMID 19461887, 2009). "Besides, LAPTM5 is critical for inducing non-apoptotic cell death in tumor parenchymal cells since its downregulation leads to inhibition of the cell death pathway in the tumor parenchyma and subsequent enhanced tumorigenesis." (PMID 39281638, 2024). "Therefore, the positive prognostic value of high CD40 and LAPTM5 expression is attributed to the tumor tissue and not to the immune cells." (PMID 32582531, 2020).
tumor (continued). "A qRT-PCR analysis of paired ESCC samples (primary tumors and their corresponding non-cancerous tissues) revealed a more than 30% reduction of LAPTM5 expression in primary tumor tissues compared with the corresponding non-cancerous tissues in 12 of the 32 cases (37.5%)." (PMID 27058622, 2016). "Based on these findings, we proposed that LAPTM5, CSF1R, SLCO2B1 and C1QC are mainly expressed in immune cells rather than LUSC cells in tumor samples." (PMID 33428598, 2021). "In our study, we demonstrated that NDV infection causes post-transcriptional degradation of both LAMP1 and LAMP2 proteins in various tumor and avian cells, while it does not significantly affect the expression of other lysosomal membrane proteins including LAMP3, LIMP II, and LAPTM5." (PMID 38354122, 2024).